IL6 (interleukin 6)
Diseases named in the same sentence as IL6 in open-access papers (continued):
Sharing a sentence is not in itself a finding about the gene and the disease.
COVID-19 (continued). "In addition, increased levels of plasma pro-inflammatory cytokines such as Interleukin (IL)-1β, IL-6, IL-8, and tumor necrosis factor-α (TNF-a) are observed in severe COVID-19 patients, indicative of a cytokine storm and subsequent ARDS development." (PMID 32695122, 2020). "Compared with non-HD patients with COVID-19, the proportion of T cell counting and plasma cytokines such as IL-4, IL-6, IL-10, TNF-α, and INF-γ was lower in HD patients infected by SARS-CoV-2." (PMID 32984768, 2020). "IL-6-induced high levels of C-reactive protein (CRP) are typically more related to bacterial rather than to viral infections: in COVID-19 patients CRP values are very variable." (PMID 32849666, 2020). "As the current evidence supporting the use of IL-6 inhibitors for treating COVID-19 is weak, professional societies do not recommend its use outside clinical studies." (PMID 33364959, 2020). "Moreover, our data indicate that IFN treatment protects against worsening lung abnormalities in COVID-19 patients and limits the effects of SARS-CoV-2 infection on reducing CD8+ T cells and increasing IL-6 and TNF-α levels." (PMID 33396578, 2020). "Discrete production of IL-6 was detected in the liver, which was not present in the liver of a non-COVID-19 control, suggesting a role for IL-6 in tissue inflammation and the resulting damage." (PMID 32957548, 2020). "In the present study, we investigated the distribution of genetic variations in IL6 and IL6R genes, which may be employed as prognostic and pharmacogenetic biomarkers for COVID-19 and neurodegenerative diseases." (PMID 33339153, 2020). "Furthermore, peripheral blood levels of CCL5 and IL-10 were increased earlier than IL-6 and IFN-γ in severe COVID-19 patients." (PMID 32766256, 2020). "Of note, the percentage of IL-6+ monocytes in patients with severe COVID-19 without ex-vivo restimulation was comparable to that observed in monocytes from healthy volunteers following R848 stimulation." (PMID 32503877, 2020). "Laboratory examinations showed that pneumonia patients had higher circulating levels of neutrophils proportion, IL-6, very low count (< 190/μl) of CD8+ T cells, and neutrophil/lymphocyte ratio (NLR) than did pneumonia-free COVID-19 patients at the 1st day after admission to hospital." (PMID 33239109, 2020). "IL-6 is a cytokine that is strongly correlated with inflammation and severity in SLE and COVID-19." (PMID 33193418, 2020). "The WHO, CDC, and FDA have not taken a position on the use of Tocilizumab in COVID-19, even though China's National Health Commission recommends it for use in COVID-19 patients but only if elevated IL-6 levels are present." (PMID 32733907, 2020). "In this regard, the only two patients to have been diagnosed as having COVID-19, despite negative PCR and serology, had typical COVID-19 features, including severe lymphopenia coincident with symptoms, pneumonia and increased D-Dimer and IL-6 levels." (PMID 32708750, 2020). "Gamma-linolenic acid, as a bioactive lipid, inhibits the production of pro-inflammatory IL-6 and TNF-α and could be employed to treat cytokine storm that is seen in COVID-19 patients." (PMID 33244381, 2020). "It was also detected that SARS-CoV-2 infects macrophages and triggers secretion of IL-6, which might contribute to lymphocyte apoptosis, suggesting an excessive infiltration and intense pro-inflammatory activity of IMM in COVID-19 patients." (PMID 32760407, 2020). "Based on the results expected with tocilizumab and siltuximab, other anti-IL-6 drugs, currently approved for rheumatoid arthritis, namely sarilumab and sirukumab, could be studied in ARDS and pneumonia patients with COVID-19." (PMID 32527304, 2020). "Together with the inflammatory cytokine IL-6 and ferritin, TnT may be used to predict the outcome of the SARS-CoV-2 infection and help to reduce COVID-19 mortality." (PMID 32548750, 2020).
COVID-19 (continued). "Therefore, we propose that anti-inflammatory strategies targeting not only inflammatory cytokines, including TNF, IL-1β, and IL-6, but also pathological IFN-I response needs to be investigated for the treatment of patients with severe COVID-19." (PMID 32651212, 2020). "Nonetheless, these data further support our findings that IL-6 levels in particular — while elevated above levels found in healthy subjects — are not markedly elevated in all severe COVID-19 patients compared with other critically ill patients." (PMID 32706339, 2020). "In both mild and severe cases of COVID-19, increased levels of IL-6 are typical, while this is not the case among asymptomatic patients." (PMID 32991323, 2020). "Inhibition of IL-6 related signalling pathways via blocking IL-6 or IL-6 receptors (IL-6R) is a promising approach to prevent CRS/cytokine storm syndrome and rapid, severe, and serious deterioration during SARS-CoV-2 infection and transition to COVID-19." (PMID 32668803, 2020). "A retrospective study of 21 patients identified significant elevations of plasma IL-6, IL-10, TNFα and IL-2 receptor in severe (n = 11) compared to moderate (n = 10) cases of COVID-19, whereas IL-1β and IL-8 levels were not significantly different." (PMID 32629875, 2020). "This study did not measure the levels of IL-6 in blood plasma or serum directly, but is consistent by our observation of elevated levels of IL-6 in COVID-19-S patients." (PMID 34676126, 2020). "In addition, EAT obtained from subjects with obesity tend to present higher levels of IL-6 and TNF-α, cytokines abundantly secreted in COVID-19 patients." (PMID 32849309, 2020). "Laboratory values in the pneumonia control group (LDH, CRP, IL-6) were not significantly different compared to COVID-19 ARDS cases." (PMID 33123171, 2020). "Previous studies have reported that the elevation in IL-6, IL-10, and IFN-γ levels in CRS, including CAR T cell therapy and severe COVID-19, is a typical phenomenon in HLH/MAS, wherein activated macrophages or T cells are the major producers of proinflammatory cytokines." (PMID 32826331, 2020). "The mechanism leading to elevated IL-6 in severe COVID-19 is not currently clear, but is likely driven through activation of virus-specific PRRs." (PMID 33101306, 2020). "Our study confirmed that COVID-19 patients with comorbidities showed more pronounced leukopenia, lymphopenia, hypokalemia, hypoalbuminemia, coagulation disorders and higher levels of inflammatory indices ESR, CRP, IL-6, and IFN-γ." (PMID 33232277, 2020). "We performed a retrospective analysis of COVID-19 patients in Wuhan, China and revealed that in COVID-19 patients, PT, glucose level, hs-CRP, PCT, IL-6, and fibrinogen were above the normal reference range, while haemoglobin was below the normal reference range." (PMID 33308159, 2020). "Indeed, patients with COVID-19 who displayed measurably higher levels of IP-10 (CXCL10), IL-10, and IL-6 when first admitted to hospital went on to become more severely ill." (PMID 33363221, 2020). "Besides, the role of IL-6 in CRS and how it interacts with the innate and adaptive immune system in the settings of COVID-19 still needs further investigation." (PMID 33195318, 2020). "Our random effects meta-analysis of 5 clinical studies of COVID-19 revealed that there was an increase of IL-6 levels in patients with severe COVID-19 compared to those with non-severe COVID-19." (PMID 33156843, 2020). "Tocilizumab, a monoclonal antibody capable of inhibiting IL-6, has resulted in a clear improvement of health in patients affected by COVID-19, although not all patients were sensitive to this treatment." (PMID 32973818, 2020). "Additionally, the levels of CD4+T and CD8+T and IL-6, IL-10, and NLR are potentially useful for predicting the development of COVID-19 and the severity of illness." (PMID 33134384, 2020).
COVID-19 (continued). "In support of these data, a study of 522 hospitalized COVID-19 patients reported a negative correlation between T cell numbers and serum IL-6, IL-10 and TNF-α levels." (PMID 32695122, 2020). "Alternatively, given that IL-6 and TGF-β seem to be available in severe COVID-19 patients, the differentiation of the common precursor T-cells to Tregs and Th17 cells may be blocked by unidentified factors." (PMID 33178221, 2020). "Hydroxychloroquine, a drug that has been investigated in COVID-19, is also known to modulate the cytokine response and reduce IL-6 levels, though recent observational studies have not identified a clear benefit in COVID-19." (PMID 32992282, 2020). "Nevertheless, in a retrospective, multicenter cohort study, the same research group reported a significant elevation of IL-6 levels in patients not surviving COVID-19 as compared with survivors." (PMID 32948252, 2020). "A second hypothesis is an increased peripheral blood frequency of a subset of polyclonal GM-CSF+ CD4 T cells capable of prodigious ex-vivo IL-6 and IFN-γ production, which has been described in COVID-19, although only in critically ill patients." (PMID 33335532, 2020). "Reports suggests that the hyperinflammation seen in severe COVID-19 may be driven by considerable levels of C-reactive protein (CRP) and Interleukin (IL)-6, resembling “cytokine storms” seen in other comparable conditions such as during CAR T cell therapy." (PMID 33303843, 2020). "At present, controlled evidence indicates that IL-6 inhibition is marginally o not effective for COVID-19, whereas several uncontrolled studies evaluating IL-1 inhibition yielded overall promising results and are awaiting validation in controlled settings." (PMID 33442386, 2020). "Overall, available evidence from RCTs indicate that IL-6 inhibition is marginally or not effective for the treatment of COVID-19." (PMID 33442386, 2020). "Severe COVID-19 cases had significantly higher blood level of procalcitonin (SMD = 0.72, 95%CI: 0.34;1,11; P-value: < 0.001; n = 1509), interleukin-6 (SMD = 0.93, 95%CI: 0.25;1.61; P-value: 0.007; n = 875),and C-reactive protein (SMD = 1.34, 95%CI:0.83;1.86; P-value: < 0.001; n = 1974)." (PMID 32879731, 2020). "Subgroup analysis according to various continents where these studies were implemented showed that studies in American patients did not support the effectiveness of anti-IL-6 signaling agents on mortality from COVID-19." (PMID 33384605, 2020). "Ongoing trials directly and indirectly target COVID-19-related endothelial dysfunctions: i.e., a virus-cell entry using recombinant ACE2 and TMPRSS-2 blockade, immunomodulatory therapies such as anti-IL-6 strategies, complement blockade, and coagulation activation." (PMID 32546188, 2020). "The use of inhibitors to bradykinin, SP, IL-6, their receptors, or the downstream signal JAK2 in the kallikrein-kinin system may provide supportive therapy and modulate the COVID-19 inflammatory response in various clinical trials currently in progress." (PMID 32922297, 2020). "SARS and COVID-19 do not lead to the upgrade of TNF-α, but the increase of IL-6 and IL-10 is more prevalent in COVID-19." (PMID 32754163, 2020). "In patients with COVID-19, the high serum levels of IL-6 and TNF-α are negatively correlated to T cells; contrariwise, it has been demonstrated that T cell levels were restored by reducing IL-6 and TNF-α concentrations." (PMID 32354030, 2020). "Interestingly, cytokines such as IL-1β, IL-6, TNF-α, and MCP-1 appear to be elevated in COVID-19 patients and also can induce HPSE expression." (PMID 33123154, 2020). "Subgroup analysis also revealed that studies in the USA did not support the effectiveness of anti-IL-6 signaling agents on mortality in patients with COVID-19, which was different from the pooled results of the European studies or Asian studies." (PMID 33384605, 2020).
COVID-19 (continued). "The infection-related biomarkers including SF markedly elevated in the serum as well as Inflammatory cytokines including IL-6, and TNF-α, indicating that inflammation storm may also occur and aggravate in patients died from COVID-19 during the disease." (PMID 32841294, 2020). "Specifically, in COVID-19, there is not enough evidence to conclude that inhibiting the signaling of IL-6 alone is enough to quell the ensuing cytokine storm." (PMID 33154452, 2020). "In particular, macrophage-related cytokines like interleukin (IL)-1β, IL-6, and tumor necrosis factor-α (TNF-α) were initially reported to be increased in COVID-19 infected patients compared with control subjects, with higher levels of cytokines in severe compared with non-severe infection." (PMID 33505321, 2020). "Role of bacterial products possibly of lung origin in augmenting the inflammatory cytokine response in severe COVID-19 was indicated here as enhanced levels of bacterial DNA and LPS in plasma positively correlated with plasma levels of EN-RAGE, TNFSF14, OSM, and IL-6." (PMID 33133083, 2020). "COVID-19 is usually accompanied by an elevation of numerous bioactive factors such as IL-1β, TNF-α, IL-2, IL-7, IL-8, IL-9, IL-17 G-CSF, interferon (IFN)-γ, XXC-10, CCL-2 CCL-3, CCL-4, and especially IL-6, which is produced predominantly by macrophages." (PMID 33114676, 2020). "COVID-19 invade the human body by combine to ACE2 receptor, resulting in excessive activation of T cells, and producing large amounts of pro-inflammatory cytokines and chemokines such as IL-6, GM-CSF." (PMID 32983254, 2020). "As a result, minimizing IL-6 plasma concentrations and controlling ACE2 gene epigenetically might be a target for prevention and therapy in COVID-19." (PMID 32758273, 2020). "Previous clinical study already demonstrated that losmapimod (p38 inhibitor) is involved in the reduction of pro-inflammatory biomarkers such as CRP and IL-6; therefore, the FDA approved phase III clinical study of losmapimod as a potential treatment for COVID-19 (LOSVID clinical trial)." (PMID 32796683, 2020). "NF-κB, IL-6, TNF are considered to be therapeutic targets for COVID-19." (PMID 33041797, 2020). "Second, levels of EBV viremia correlate with IL-6 in COVID-19 patients but not in non-COVID-19 patients." (PMID 33228750, 2020). "IL-6 was higher in patients with COVID-19 with an unfavourable outcome than in those without (median 94.7 vs 30.7, p=0.034)." (PMID 33328246, 2020). "Interleukin 6, which is significantly increased in COVID-19 patients compared to healthy subjects (but without differences compared to ICU patients), is another key regulator of immune-related reaction." (PMID 33182653, 2020). "Our data reveal that prophylactic doses of LMWH is associated with reduced HPSE activity in moderately diseased COVID-19 patients while this reduction of HPSE activity with LMWH prophylaxis was not accompanied with a reduction in HS or IL-6 plasma levels." (PMID 33123154, 2020). "Also, the manuscript focuses on the role of D-dimer, fibrinogen, and interleukin-6 (IL-6) in development and investigating VTE in COVID-19 patients." (PMID 33223833, 2020). "The typical ARDS features found in severe COVID-19 has a cytokine profile comparable to H1N1(2009) infection where elevation of IL-6, IP-10 was observed in severe but not mild disease." (PMID 32824753, 2020). "When administered early in the onset of the cytokine storm phase, it is possible that rapamycin prevents progression to severe forms of COVID-19 through the down-regulation of SASPs, of the mTOR-NLRP3-IL-1β axis, of the IL-6 pathway, and of senescent T-cell counts." (PMID 33361522, 2020). "The phenomena suggests that the decrease of T cells seen in COVID-19 patients may be the result of high serum concentration of TNF-α, IL-6, and IL-10 negatively regulating T cell survival or proliferation." (PMID 32425950, 2020).
COVID-19 (continued). "The upper limit point of serum IL-6 level in COVID-19 patients who had no severe pneumonia was reported 24.3 pg/mL, and the increased expression of IL-6 in serum is expected to predict the severity of the COVID-19 pneumonia and a poor prognosis of patients." (PMID 32819292, 2020). "Ex vivo examination of intracellular cytokine levels has revealed an increased frequency of GM-CSF+ and IL-6+ monocytes in both ICU and non-ICU COVID-19 patients, with the percentage of IL-6+ monocytes correlating with disease severity." (PMID 33123152, 2020). "Also, the level of proinflammatory cytokines, such as interleukin 6 (IL-6), IL-2, IL-10, and tumor necrosis factor alpha (TNF-α), highly increases in the serum of severe COVID-19 cases." (PMID 33262791, 2020). "A case report study, treating a child with Crohn's disease and affected by COVID-19, used anti-TNF (Infliximab) with positive results, demonstrated by an improved cytokine profile, with normalization of TNF-α, and a decrease of IL-6 and IL-8 concentrations in blood." (PMID 33426096, 2020). "Thus, our data demonstrates a marked dysregulation of the cytokine network in COVID-19 patients and for MCP-1 and IL-6, the levels were strongly correlated with the degree of RF." (PMID 33303843, 2020). "Researchers have identified that the SARS-CoV-2 virus increases the expression of multiple proinflammatory cytokines (TNF-α, IFN-γ, IL-6, and MCP1) in the serum, indicating that the inflammatory storm may be involved in the progression of COVID-19." (PMID 32494546, 2020). "This is not, however, restricted to IL-6 and in fact elevated levels of a bundle of pro-inflammatory cytokines has been reported in severe COVID-19 cases." (PMID 33066821, 2020). "The plasma level of IL-6, considered as a significant cytokine contributing to MAS, increases both in mild and severe patient groups of COVID-19: severe patients have a significantly higher level of IL-6 than mild or nonsevere patients." (PMID 32299202, 2020). "When we compared historical and present control subjects who had normal cognition (no viral illness), we found that patients with COVID-19 and neurologic symptoms had increased CSF levels of IL-6, IL-8, IL-10, IP-10, and TNF-α." (PMID 32487282, 2020). "The basal circulating IFN-γ levels were comparable with c-reactive protein in the discrimination of the occurrence of lung fibrosis among COVID-19 patients at discharge, unlike circulating IL-6 levels." (PMID 33133104, 2020). "IL-6 also induces hepatocytes to synthesize acute phase reactive protein, especially Serum amyloid A (SAA) and C-reactive protein (CRP), which were significantly elevated in COVID-19 patients." (PMID 33195318, 2020). "This retrospective cohort study on COVID-19 patients with AHRF showed that age older than 60 years, thrombocytopenia, elevated levels of IL-6 at HFNC initiation, and an ROX index <5.31 within the first 4 h of HFNC therapy initiation were independent predictors of HFNC failure." (PMID 33425951, 2020). "Specially, an analysis on peripheral blood mononuclear cells from 14 patients in deteriorated condition from COVID-19 and 3 healthy controls revealed that COVID-19 patients have higher levels of both PD-1 and TIM-3 as well as remarkably elevated serum levels of IL-6, IL-10, and TNF-α." (PMID 32967229, 2020). "A meta-analysis including nine studies found that patients with severe COVID-19 had a significantly higher serum IL-6 levels compared to non-severe patients, and increased IL-6 levels are correlated with elevated mortality in patients." (PMID 33195318, 2020). "Baseline characteristics were comparable between these two groups table 5Comparison between patients with COVID-19 with and without MetS showed that IL-6 was lower in patients with COVID-19 with MetS (median 70.01 vs 30.60 pg/mL, p=0.028)." (PMID 33328246, 2020).